LEP (leptin)
Diseases named in the same sentence as LEP in open-access papers (continued):
Sharing a sentence is not in itself a finding about the gene and the disease.
Obesity (continued). "Diet‐induced DNA methylation changes occurring within ARC genes, particularly POMC and INS‐R, which prevents an appropriate response to leptin and insulin, thereby affecting energy homeostasis, subsequently leading to the development of obesity and MeS." (PMID 31660128, 2019). "Once the pivotal trial for obesity was declared a failure, the availability of leptin, and both its funding for and interest in its study, rapidly diminished." (PMID 30357355, 2019). "It is well established that the protein tyrosine phosphatase PTPN1 directly regulates the insulin and the leptin signaling pathway, making it a promising therapeutic target for type II diabetes and obesity." (PMID 31527306, 2019). "Among adipokines, leptin, whose circulating levels increase proportionally to total adipose tissue mass, has been identified as a key member of the molecular network in obesity." (PMID 30634494, 2019). "In turn, through over-production of long-chain fatty acid (LFA) and leptin by expanding adipocytes, obesity is accompanied with general immune suppression including aberration of antiviral IFN signaling, which leads to high susceptibility to viral infections." (PMID 31726661, 2019). "Obesity induces abundant leptin production, however, reduced sensitivity to leptin leads to the development of metabolic disorders, so called leptin resistance." (PMID 31141984, 2019). "Commonly, a higher level of leptin follows obesity, however, leptin appears to be ineffective against excessive AT accumulation." (PMID 31408957, 2019). "Among them, CNTF is the cytokine attracting the strongest interest, due to its anti-obesity effect in animal models as well as in leptin-resistant obese patients." (PMID 31781039, 2019). "Obesity is also associated with reduced transport of proteins across the BBB that act on the CNS to regulate feeding, such as leptin, insulin, and ghrelin." (PMID 30986918, 2019). "Leptin has been the focus of intensive research in order to characterize its protective anti-obesity role, particularly during developmental stages." (PMID 31661820, 2019). "Obesity and the MS are distinguished by an increase in circulating leptin concentrations, in parallel to a drop in the levels of adiponectin." (PMID 30813240, 2019). "Overall, these results demonstrate that leptin serves as a potential intervention to decrease obesity by inhibiting the Hh signaling pathway." (PMID 31022919, 2019). "Similar to neuronal-specific PTP1B deletion, POMC-specific deletion of PTP1B rendered mice resistant to diet-induced obesity, increased energy expenditure, enhanced leptin and insulin sensitivity and improved glucose homeostasis." (PMID 31319588, 2019). "The adiponectin/leptin ratio in patients with obesity and diabetes is significantly lower than that in patients without obesity." (PMID 31144666, 2019). "During obesity, there is an imbalance between insulin‐stimulated leptin‐induced anorexigenic and orexigenic signaling." (PMID 31660128, 2019). "Steppan's group showed in the ob/ob mice model that obesity-induced bone growth was mediated by leptin, the product of the obese gene, via its signaling receptor (ObRb)." (PMID 31019532, 2019). "Plasma levels of leptin are altered in several pathological conditions, including cardiovascular diseases, obesity, and reproductive disorders." (PMID 29910808, 2018). "When it was discovered, leptin monotherapy was envisioned to cure the overwhelming worldwide epidemic of obesity and its metabolic comorbidities." (PMID 30587816, 2018). "IKKβ/NF-κB, as a mediator of metabolic inflammation, is a new strategy to combat obesity and its related diseases via regulating central insulin/leptin signaling and action." (PMID 29930535, 2018). "Leptin is known as a proinflammatory adipokine, secreted by the white adipose tissue, and considered crucial for the development of hypertension in obesity." (PMID 30514305, 2018).
Obesity (continued). "The increase in leptin production seems to trigger an increase in the infiltration of immune cells into visceral adipose tissue (VAT) in response to obesity." (PMID 29875681, 2018). "Our results demonstrate that ablation of Lgr4 in mice resists dietary and leptin mutant-induced obesity and its metabolic complications, and further prove the crucial role of LGR4 in obesity." (PMID 30065654, 2018). "Further investigations need to clarify the molecular mechanisms involving leptin-reactive IgG in leptin resistance, obesity, and diabetes." (PMID 29795184, 2018). "Leptin secretion is proportional to the total amount of adipose tissue, and its serum concentration increases significantly in obesity." (PMID 30593267, 2018). "In summary, our findings provide new mechanistic insight on earlier data showing that obesity is accompanied by a decrease in the protein bound forms of leptin and an increase in free leptin in plasma." (PMID 29795184, 2018). "Further studies are needed to better understand the correlation between leptin levels and NK cell development and function, as well as the potential implications in obesity." (PMID 29910742, 2018). "Thus, increased leptin levels may support the association between MS etiology and obesity." (PMID 29525910, 2018). "Diet-induced obesity in mice fed with HFD results in an elevation of serum leptin levels and splenic CD11c+ DCs, with diminished DC cell stimulatory capacity, being these effects distinct from that caused by HFD alone in obese-resistant mice." (PMID 29910742, 2018). "Mechanically, it is suggested that, as obesity advances, leptin secreted by adipocytes stimulates IFN-γ production from CD4+ T cells, which further promotes adipocyte MHCII expression and thus Th1 differentiation, leading to a vicious cycle of AT inflammation." (PMID 30233575, 2018). "Anorexigenic factors, such as refeeding, leptin or diet-induced obesity, a condition characterized by increased plasma leptin concentrations, are associated with reduced hypothalamic AMPK activity." (PMID 29433631, 2018). "Obesity also leads to dramatic increases in circulating levels of leptin, a hormone produced in adipose tissue." (PMID 29675134, 2018). "Selective ARC resistance to leptin has been reported previously as a consequence of diet-induced obesity." (PMID 30043179, 2018). "Leptin is a hormone secreted by adipocytes in proportion to adipocyte mass and is therefore increased in obesity and decreased in malnutrition." (PMID 29868016, 2018). "When we investigated the impact of both obesity and Tx treatment, Leptin and VEGF expressions were decreased in MCF-7 cells co-cultured with MA30 and Tx (R = 0.44, p<0.05; R = 0.51, p = 0.05, vs co-cultured with MA20 and Tx)." (PMID 29389973, 2018). "There are several plausible mechanisms relating to elevation and obesity, including socioeconomic status, nutrition, hypoxia, mean annual temperatures, physical activity, leptin signaling, and metabolic demands." (PMID 30631785, 2018). "While the effects of obesity on sepsis remain controversial, leptin's detrimental role in sepsis has been documented in several studies." (PMID 30046592, 2018). "Antagonists at CB1 have been demonstrated to restore hypothalamic leptin sensitivity reducing obesity in diet-induced obese (DIO) mice." (PMID 30201891, 2018). "Increased intra-abdominal pressure, gastroesophageal reflux and altered levels of adipokines and cytokines (leptin, TNFα, IL-6 and IL-17) from obesity have been proposed as potential GCA promoting factors and reviewed in depth." (PMID 30567335, 2018). "The physiology and regulation of leptin also need to be fully clarified, as the notion of leptin as an anorectic, anti-obesity hormone has been expanded to emphasize leptin’s role as a rapid signal of starvation or energy deficit." (PMID 29434574, 2018).
Obesity (continued). "Many candidate gene and genome-wide association studies (GWAS) have been carried out where LEP and LEPR polymorphisms have been investigated for their role in measures of adiposity, obesity and its sequelae." (PMID 30121879, 2018). "In obesity-induced animals, decreased adiponectin levels and increased leptin levels in the plasma have been observed." (PMID 30200239, 2018). "The situation appears to be most exacerbated in cases of extreme obesity where a strong positive correlation exists between the responsiveness of the MMP-13 gene to leptin and the BMI of osteoarthritic individuals." (PMID 29971011, 2018). "Leptin, cloned in 1994 from white adipocytes, functions initially as an ob gene to reduce obesity by controlling appetitive behaviors via hypothalamic neurons." (PMID 30319532, 2018). "In the present study, an elevated plasma leptin/ApN ratio was found in cortico-treated mice, compared to controls, suggesting the onset of obesity and metabolic syndrome." (PMID 30115912, 2018). "Most studies on LR have focused on exploring the mechanisms to reducing obesity using leptin, but ignored leptin original function from the perspective of adaptive evolution." (PMID 30405527, 2018). "The main outcome measures included fecal microbiota ecology (by 16S rRNA gene sequencing), psychiatric disorders including opioid use, and circulating leptin and oxytocin as representative hormone biomarkers for obesity and psychological pro-social behavior." (PMID 29596446, 2018). "Diabetes and obesity are diseases of insulin and leptin resistance, in which the signaling responses to the hormones are attenuated." (PMID 29348454, 2018). "It is important to point out that during the early stages of development, the fructose ingestion, lowers the levels of the anorexigenic hormone, leptin, and perhaps initiates re-setting of central mechanisms that can lead to obesity." (PMID 30374065, 2018). "Accordingly, we generated a diagram to reveal the selective blockade of leptin action in metabolic regulation when obesity was induced in fish by feeding on an HCD or HFD." (PMID 30405527, 2018). "Pre-clinical studies have demonstrated a possible correlation between obesity-induced hormones (leptin and IGF-1) and PDAC chemoresistance via augmented epithelial-to-mesenchymal transformation (EMT)." (PMID 30366466, 2018). "Mechanistically, this phenomenon seems to occur via decreased DNA methylation of the imprinted IGF2 gene in the offspring and hypermethylation of two obesity-related genes—leptin and TNF." (PMID 29480368, 2018). "In contrast, KD values correlated positively with plasma leptin levels and obesity traits in our cohort, and with diabetes markers in both the total cohort and in the obese T2D group." (PMID 29795184, 2018). "To this aim, we took advantage of the Zucker (fa/fa) rat model, which exhibits obesity, fatty liver and elevated leptin and adiponectin levels." (PMID 29959379, 2018). "KDM3A−/− mice have many of the signs of metabolic syndrome including insulin resistance, hypertriglyceridemia, elevated leptin levels, and obesity." (PMID 29922517, 2018). "Increasing the dietary amount of fat from 10 to 45% or 60% resulted in obesity accompanied by increased leptin, fasting blood glucose and insulin, and reduced glucose tolerance." (PMID 30670942, 2018). "In fact, it has been proposed that the increment of TSH in obesity is a paraphenomenon similar to insulin resistance, in which leptin is the responsible for rising levels of thyrotropin, being the resistance in TSH receptors a consequence of this process." (PMID 30151097, 2018). "Intensive research in the field is now aimed at better understanding the molecular mechanisms that leptin triggers in tumor cells and discovering new molecular targets for therapy in patients with breast cancer and obesity." (PMID 30404206, 2018).
Obesity (continued). "Leptin resistance or desensitization of signaling in obesity (BMI ≥ 30 kg/m2) and over-nutrition impaired antigen-specific IgG response as well as reduced CD69, IFN-γ, and Granzyme-B in CD8+ T cells to influenza vaccination." (PMID 29868503, 2018). "They demonstrated that resistin, leptin, and TNF-α are associated, independently of obesity and waist circumstance, with chronic venous disease." (PMID 29720688, 2018). "POMC-specific induction of XBP1s expression led to the decrease of leptin and insulin resistance, as well as diet-induced obesity even under treatment with strong activators of ER stress like tunicamycin and thapsigargin." (PMID 29921793, 2018). "We will focus on the actions of leptin and adiponectin, two of the most abundant and well studied adipokines, in the brain, with particular emphasis on how altered signaling of these adipokines in obesity may lead to cognitive dysfunction and augmented risk for Alzheimer’s disease." (PMID 30692905, 2018). "In mice and humans, leptin is an adipostatic hormone that regulates adipose mass, and failure of leptin signaling results in hyperphagia and obesity." (PMID 30177968, 2018). "Leptin exerts its roles through the leptin receptor; therefore, the leptin receptor gene is considered a biological pathway related to obesity development." (PMID 30338250, 2018). "Our novel findings point to a potential link between obesity-related leptin secretion and breast cancer through cell oxidative status, which contributes to the aggravating effect of obesity in breast carcinogenesis." (PMID 30563501, 2018). "Obesity is a state of elevated concentration of leptin in the blood, at the same time, it is related to tissue resistance to leptin." (PMID 29369197, 2018). "In summary, this study demonstrates that chronic exposure to NP-1 exerted anti-obesity and anorexic actions in a scenario with limited leptin and adiponectin bioactions." (PMID 29959379, 2018). "In the model including BMI as a continuous variable instead of obesity with adjustment for age, sex, BMI and tPa, elevated leptin and decreased adiponectin also predicted PTS and the C-statistic was 0.9." (PMID 29720688, 2018). "Increased plasma triglyceride levels are a key feature of obesity and would play an important role in leptin resistance." (PMID 30618559, 2018). "Some of the consequences of overnutrition-induced obesity are hyperinsulinemia and hyperleptinemia, resulting in insulin and leptin resistance respectively." (PMID 30202241, 2018). "Of the new loci identified, EPAC1 (RAPGEF3) is known to play a role in energy homeostasis, diabetes and obesity propensity and regulates insulin and leptin signalling." (PMID 30121879, 2018). "Leptin resistance, a general feature of obesity, IR, and diabetes, characterizes the inability to detect satiety despite abundant energy stores and high levels of leptin." (PMID 29921793, 2018). "Obesity disrupts serum levels of leptin, ghrelin, adiponectin, orexin, obestatin and other metabolic hormone profiles." (PMID 30205828, 2018). "Obesity increases the production and release of pro-inflammatory adipokines, including leptin and IL-6." (PMID 29949600, 2018). "Leptin and lipocalin-2, which are mainly produced in adipose tissues, are up-regulated in obesity and lead to the development of insulin resistance." (PMID 29783731, 2018). "Previous studies showed that low birth weight is one of the factors leading to obesity, diabetes, increased leptin levels, as well as MS development in the future." (PMID 30636232, 2018). "Leptin concentrations are correlated with the adipose tissue mass and leptin insensitivity is often observed in obesity." (PMID 30103773, 2018). "Obesity is thought to induce a proinflammatory state and adipose tissue releases signals including leptin, TNF-alpha and IL-6." (PMID 30631374, 2018).
Obesity (continued). "Milk hormones involved in the regulation of energy balance and metabolic development of the neonates, such as leptin, ghrelin, and adiponectin, have received considerable attention in the context of the current metabolic syndrome and obesity epidemics." (PMID 30319659, 2018). "While leptin deficiency strongly induces feeding and a decrease in energy expenditure, metabolic disorders such as obesity go along with elevated leptin levels but altered responses to leptin, often termed “leptin resistance”." (PMID 29849009, 2018). "For instance, adipokines, such as leptin, TNF-alpha and resistin, have a pro-inflammatory role and are associated with an increased risk of obesity comorbidities such as T2D and cardiovascular diseases." (PMID 30451909, 2018). "Obesity concomitant with arsenic exposed mice showed a remarkable leptin resistance and higher circulating levels of leptin that is in agreement with our research." (PMID 29755549, 2018). "In conclusion, the joint exposure of mice to obesity and DEHP caused pathological damage to the Leydig cells, increased serum leptin levels, and caused reductions in sperm count, motility, relative epididymis weight, and testosterone level." (PMID 29887939, 2018). "The protein tyrosine phosphatase1B (PTP1B) is a negative regulator of both insulin and leptin signaling, and shows a highly validated therapeutic target for the treatment of diabetes and obesity." (PMID 29593573, 2018). "High leptin levels lead to obesity, and the administration of leptin has also been shown to increase depressive-like behaviors in mice." (PMID 29615964, 2018). "A study with follow-up to age twenty found higher overweight and obesity rates as well as higher concentrations of total and low-density lipoprotein cholesterol, leptin and apolipoprotein B in those born by CS29." (PMID 30310162, 2018). "Rare human cases where leptin, or the leptin receptor, is entirely ablated have subsequently been reported and uniformly exhibit severe obesity." (PMID 30121879, 2018). "LEPR activity on astrocytes has been proposed to actively regulate leptin transport across the blood brain barrier, a finding consistent with evidence that central regulatory changes of LepR during obesity and inflammation often occur in astrocytes." (PMID 30231941, 2018). "The multivariable logistic regression model adjusted for age, sex, obesity, and tPa showed that increased leptin (values >32.1 ng mL−1) and decreased adiponectin (values ≤12.8 μg mL−1) levels predicted PTS." (PMID 29720688, 2018). "The observation that genetic interventions that disrupt neuronal inflammation can block both obesity and hypothalamic leptin resistance during feeding with a high-fat diet supports such role of inflammation in NAFLD pathogenesis." (PMID 28643267, 2018). "In this context, the potential role of CRP in modulating the action of leptin in obesity is relevant." (PMID 29910808, 2018). "We also showed that cytotoxicity of Natural Killer cells declined under leptin in obesity condition." (PMID 30563501, 2018). "We also confirmed that D2R levels were lower in HF-fed animals, also consistent with other obesity D2R studies and D2R-dependent mechanisms of insulin and/or leptin signaling." (PMID 29698491, 2018). "In consequence, the drugs that improve leptin resistance will present significant anti-obesity effects." (PMID 29874843, 2018). "Obesity can dramatically impact neutrophil migration through leptin signaling as well as impact neutrophil oxidative capabilities." (PMID 29497602, 2018). "There is evidence that individuals and animals with obesity do not show the same sensitivity to the satietogenic effects of cholecystokinin (CCK) when compared to eutrophic, and the resistance to leptin is increased especially in the state of obesity." (PMID 29322840, 2018). "Energy homeostasis is regulated by the hypothalamus but fails when animals are fed a high-fat diet (HFD), and leptin insensitivity and obesity develops." (PMID 30519364, 2018).